FUT4 (fucosyltransferase 4)
Diseases named in the same sentence as FUT4 in open-access papers (continued):
Sharing a sentence is not in itself a finding about the gene and the disease.
tumor (continued). "The expression of miR-200b and FUT4, as well as the PI3K/Akt signaling pathway activation, in the xenografted tumor tissues were analyzed by using real-time PCR, western blotting and immunohistochemical staining." (PMID 28692034, 2017). "The CD3+ T cells were the most abundant in all tumor locations (at the invasive front, stroma and intraepithelial), followed by infiltrating CD68+ monocyte–macrophage and CD15/FUT4+ neutrophils, respectively." (PMID 26427914, 2015). "Besides, fucosyltransferase IV (FUT4) and its synthetic tumor sugar antigen Lewis Y (LeY) are severely elevated in various solid tumors and play an important role in tumor invasion and metastasis." (PMID 33224886, 2020). "Together our data indicate that FUT4 and FUT9 may have overlapping, yet also unique biosynthetic properties regarding the modification of the substrate N-glycome in tumor cells." (PMID 30476078, 2019). "In this cohort, CD15/FUT4 overexpression was associated with short time-to-recurrence (TTR) but not with OS, independently from initial tumor stage." (PMID 26427914, 2015). "Among 102 assessable tumor specimens, 31 out of 44, (70 %), 8 out of 40 (20 %) and 1 out of 18 (6 %) of the CD15/FUT4-high, low and negative tumors were considered nonresponders to the therapy, respectively (P = 0.00000532)." (PMID 26427914, 2015). "Interestingly, higher FUT4 mRNA level was determined in CRC tumor tissues than the adjacent nontumor tissues and in cases of distant metastasis than those of no metastasis." (PMID 32209115, 2020). "As LY6G6D and FUT4 tended to be upregulated in MSS (typically poorly immunogenic), but not in MSI (typically highly immunogenic) CRC cell lines, we then analyzed other primary tumours by using GSE13294 and GSE30540 datasets, where MS status and chromosomal instability were available." (PMID 30670049, 2019). "Therefore, the progressive decrease of immune cell densities along with CD15/FUT4 overexpression and increased inflammatory response could provide a clinical context of tumor progression, explainable as a pronounced immune-escape mechanism." (PMID 26427914, 2015). "Therefore, the novel role of CD15/FUT4 reflects persistent genetic features of tumor cells rather than differences in immune infiltrates." (PMID 26427914, 2015). "Different modes of immune evasion were seen across 12 tumours with up-regulation or consistent expression of CD47, unlike other immune evasion genes such as PDL1, FUT4, CTLA4 and BTLA which were downregulated in a few samples." (PMID 28886030, 2017).
cancer (169 papers, 2009 to 2026). A tumor composed of atypical neoplastic, often pleomorphic cells that invade other tissues. "Our study shows that ALT and Brv-A has a potential inhibitory effect over STAT3 activation, FUT4, and P-GP all of which are known to be linked to the drug resistance in cancer." (PMID 35281907, 2022). "In previous studies, FUT4 has been associated in cancer development and multidrug resistance via PI3K/AKT signaling pathway." (PMID 35281907, 2022). "Together, the results reveal a network of cancer-associated FUT4 that is controlled by miR-26a/26b in CRC." (PMID 28640257, 2017). "Herein, we provide evidence that the “don’t eat me” signal CD15/FUT4 on cancer cells associates with decreased benefit to target therapy." (PMID 26427914, 2015). "We then associated cancer-related expression of CD15/FUT4 with patients’ outcome in terms of Response and Survival (PFS and OS)." (PMID 26427914, 2015). "The identified CRC-restricted miR-26a and miR-26b might be implicated in cancer progression via their target gene FUT4, suggesting their potential usage in CRC treatment." (PMID 28640257, 2017). "Previous reports identified FUT4 as a tumorigenic FUT establishing an oncogenic glycoproteome that promotes cancer metastasis." (PMID 38326303, 2024). "In CRC, miR-26a is apparently downregulated and can regulate FUT4 expression to suppress cancer cell aggressiveness." (PMID 36820066, 2023). "These experiments inhibited the expression of CD15 and CD15s by targeting their encoding genes fucosyltransferases 4,7 (FUT4 and FUT7), respectively, which thus yielded in a reduced cancer cells adhesion and preserved integrity of BBB." (PMID 37190188, 2023). "Nevertheless, FUT4 co-expression genes regulate mitosis, gene translation, and gene transcription in cancer cells." (PMID 36164349, 2022). "Numerous studies report FUT4 regulation by ncRNAs in various cancers and its contribution to malignancy." (PMID 36555445, 2022). "LncRNA-MALAT1 exerts a functional role in the cancer development as well as the drug resistance and is linked with STAT3 activation and activity of FUT4." (PMID 35281907, 2022). "TRAF7 has been partially studied in aquatic animals, and BAG3, WDR20 and FUT4 are mostly focused on wound tissue recovery and cancer treatment in medicine." (PMID 35936896, 2022). "According to the results of the analysis, FUT4 co-expression genes mainly participate in cancer cell proliferation and gene expression." (PMID 36164349, 2022). "We noted that ALDH, POU5F1 (encodes OCT3/4), CD44, FUT4 (encodes SSEA-1), and PROM1 expression were significantly downregulated in cancer cells transduced with TRβ." (PMID 34503062, 2021). "Overall, both FUT4 and its product, type II Lewis antigens, promote migration and invasion by various cancer cells, especially GC cells." (PMID 31831855, 2020). "The present study demonstrated that FUT4 gene silencing significantly increased the suppressive effects of cisplatin on cancer cell proliferation and boosted apoptosis." (PMID 32948132, 2020). "In the Cancer Genome Atlas dataset, the expression level of FUT4 (CD15) mRNA was higher in the low/intermediate-risk group for recurrence than in the high-risk group and exhibited positive correlation with SLC5A5 (NIS) mRNA expression (p = 0.003)." (PMID 32486143, 2020). "High expression of FUT4 has been found in different types of cancers, including acute lymphoblastic leukemia, colon, breast, pancreatic, lung, and GCs." (PMID 31831855, 2020). "FUT6 has also been reported to elicit similar pro-tumorigenic roles as FUT4 in various cancer types." (PMID 31450600, 2019). "Adhesion of cancer cells was significantly reduced following the knockdown of FUT4/CD15 and the number of adherent cells were less compared to the wild type (P < 0.01)." (PMID 31104223, 2019). "Overexpression of FUT4/CD15 led to an increase in endothelial cell adhesion in all studied cancer cells and FUT4/CD15 knockdown resulted in decreased adhesion." (PMID 31104223, 2019).
cancer (continued). "FUT4 has been regarded as a cancer-related fucosyltransferase and accumulating evidence demonstrated its crucial roles in the development of cancer." (PMID 28640257, 2017). "Here we aimed to find the specific microRNA (miRNA) targeting FUT4 to inhibit cancer proliferation and metastasis." (PMID 28692034, 2017). "An abnormal increase in the levels of FUT4 and LeY is observed in many cancers and correlated with cell proliferation and metastasis." (PMID 28692034, 2017). "Fucosyltransferase IV (FUT4) and its synthetic cancer sugar antigen Lewis Y (LeY) was abnormally elevated in many cancers." (PMID 26636541, 2016). "Increased FUT4 expression has been reported in many cancers, such as gastric, colorectal, and lung cancer." (PMID 25672851, 2015). "We have previously reported that FUT4 siRNA mediated deactivation of EGFR/MAPK pathway to inhibit cancer cell proliferation." (PMID 25672851, 2015). "To corroborate CD15/FUT4 cancer-related alteration and its relationship with inflammatory response and patients’ outcome, we analyzed 70 additional samples, resulting in a total of 102 patients." (PMID 26427914, 2015). "Cancer-related CD15/FUT4 overexpression participates in cetuximab or bevacizumab mechanisms of resistance in mCRC patients." (PMID 26427914, 2015). "We observed that the MEK inhibitor “Selumetinib” caused a significant reduction of CD15/FUT4 transcript, as a consequence, CD15/FUT4-high expressing cancer cells were more sensitive to “Selumetinib” and Pimasertib” than CD15/FUT4-low counterparts." (PMID 26427914, 2015). "Increased fucosyltransferase IV (FUT4) is seen in many types of cancer, and manipulating FUT4 expression through specific signaling pathway inhibits cell growth and induces apoptosis." (PMID 26094873, 2015). "We further confirmed the association between CD15/FUT4 overexpression and cancer recurrence in the GSE17536/GSE17537 series (n = 226), for which reported follow-up data were available." (PMID 26427914, 2015). "This independent cohort confirmed CD15/FUT4 positivity in the majority of carcinomas (76 %; 107 out of 140)." (PMID 26427914, 2015). "This study suggests that Catechin gallate may have a strong binding affinity for DYRK1A and FUT4, indicating its potential for treating other diseases, such as cancer and neurodegenerative disorders." (PMID 40699724, 2025). "The purpose of inhibiting STAT3 activation, P-GP and FUT4 expressions in A549/T cells was to overcome the resistivity, as these proteins are considered to be the major contributors in developing preventive strategies by cancer cells against paclitaxel." (PMID 35281907, 2022). "In conclusion, we revealed the essential role of exosomes in communication between cancer cells and demonstrated that MALAT1 expression in exosomes was required for inducing aggressiveness phenotype by regulating FUT4-associated fucosylation and PI3K/Akt/mTOR pathway." (PMID 32209115, 2020). "FUT4 could catalyze α1, 3-fucosylation that is particularly involved in a variety of pathological processes and in cancer biology." (PMID 32209115, 2020). "We found that all of the markers except FUT4 were upregulated in the cancer patients." (PMID 22496728, 2012). "However, the upstream regulator as well as the downstream fucosylated targets of FUT4 are poorly characterized and have never been associated with sex in cancer." (PMID 38326303, 2024). "Despite the relatively smaller number of cells in the ‘CD44_high’ cluster, CD44 expression, along with other cancer stem cell marker genes such as LGR5, ALDH1A1, and FUT4, was significantly higher compared to the ‘CD44_low’ cluster." (PMID 40849307, 2025). "PDAC cancer stem cell markers including CD44, MET, CD133, FUT4, ACVR1, mTOR, and KLF4 were positively related to IARS2 expression." (PMID 40092487, 2025). "For example, fucosyltransferase IV (FUT4) promotes cell proliferation via both MAPK and PI3K-AKT pathways and was found to be upregulated by HSF1 to promote cancer cell proliferation." (PMID 37153737, 2023).
cancer (continued). "After targeting three important modules responsible for paclitaxel drug resistance in cancer i.e., STAT3, FUT4, and P-GP, we were interested to determine the role of MALAT1 in this scenario." (PMID 35281907, 2022). "Compared with monolayer-culture GBM cell lines, cancer stem cell (CSC) markers such as SOX2, PROM1, POU5F1, MSI1, FUT4, and CXCR4 were upregulated in the spheroids." (PMID 34638384, 2021). "FUT4 was a member of FUT family, which contributed to biological processes, including tissue development, inflammatory response and cancer metastasis." (PMID 33981845, 2021). "Here, we wanted to further investigate the role of CD15 and CD15s on the potential transmigration of cancer cells across an intact brain endothelial monolayer by modulating CD15 and CD15s expression by targeting the FUT4 and FUT7 genes." (PMID 31104223, 2019). "Fucosyltransferase IV (FUT4) and its synthetic cancer sugar antigen Lewis Y (LeY) was aberrantly elevated in various solid tumors, it plays critical role in the invasion and metastasis." (PMID 28423676, 2017). "The Cancer Genome Atlas (TCGA) dataset was used to analyze and predict glycosyltransferases that are highly correlated with TIM-4 expression, among which the expression of FUT4 was correlated positively with TIM-4." (PMID 35433445, 2022). "Among SLs family, we chose ALT and Brv-A for the current study, as 1) the anti-cancer effect and their pivotal role in the inhibition of STAT3 signaling has been extensively reported 2) we confirmed that STAT3, FUT4, and P-GP were the common targets of ALT and Brv-A." (PMID 35281907, 2022). "PROM1, LGALS1, CD44, FUT4 and HOXA10 were identified as hub genes, which were involved in focal adhesion, calcium-dependent phospholipid binding, connective tissue development and transcriptional misregulation in cancer." (PMID 32347296, 2020). "Following this approach, we successfully generated FUT4- or FUT9-expressing MC38 glyco-engineered cell lines and examined changes in their respective glycosylation profiles, focusing on biosynthesis of the fucosylated Lewisx determinant and its impact on the cancer cell glycome." (PMID 30476078, 2019). "Compared to the PTLS‐ group, higher expression of FUT4 in the PTS+ group in paracancer (PTLS− vs. PTLS+, 12.62, 30.03, p < 0.001), and the two groups in cancer (PTLS− vs. PTLS+, 23.28, 26.24, p = 0.54) were not statistically significant." (PMID 36082777, 2022).
infection (28 papers, 2011 to 2024). The state of being infected such as from the introduction of a foreign agent such as serum, vaccine, antigenic substance or organism. "Except for the Fut4 that was not significantly altered in the Gcnt1 deficient animals, an up-regulation of the α1,3-fucosyltransferases, Fut7, 9, 10 and 11, was observed upon infection by M. tuberculosis, in line with the data obtained for C57BL/6 mice." (PMID 33406734, 2021). "At 4 h post-infection, the expression level of FUT2 was higher in GES-1 cells infected with H. pylori strain M84, P164, YN4-62, and the expression level of FUT4 was higher in GES-1 cells infected with H. pylori strain HLJ030 and YN4-62." (PMID 33557187, 2021). "The increased levels of fucose in the tissue during infection are consistent with the observed increase in transcription levels of FUT2 and FUT4, coding for enzymes transfering Fuc α-1,2 and Fuc α-1,3 respectively, on mucins." (PMID 21569362, 2011).
immune disease (1 paper, 2020). "Consequently, FUT4 downregulation could contribute to the inhibition of the PD1–PDL1 axis, with consequent recovery of the immune disease control." (PMID 33014780, 2020).
FUT4 also shares sentences with these, for which no sentence is quoted: Hodgkins lymphoma (35 papers); lymphoma (15); pancreatic cancer (12); lymph node metastasis (8); teratoma (8); adenocarcinoma (7); embryonal carcinoma (7); rheumatoid arthritis (7); thyroid cancer (7); non-small cell lung carcinoma (6); asthma (5); ependymoma (5); Stroke (5); acute myocardial infarction (4); adenoma (4); B cell lymphoma (4); heart failure (4); prostate carcinoma (4); renal cell carcinoma (4); anaplastic large cell lymphoma (3); brain cancer (3); cervical carcinoma (3); chordoma (3); chronic myeloid leukemia (3); classic Hodgkin lymphoma (3); head and neck squamous cell carcinoma (3); periodontitis (3); pilocytic astrocytoma (3); renal carcinoma (3); triple-negative breast carcinoma (3).
A further 157 diseases each share a sentence with FUT4 in 2 papers or fewer.